LALBA (lactalbumin alpha)
Description:
Regulatory subunit of lactose synthase, changes the substrate specificity of galactosyltransferase in the mammary gland making glucose a good acceptor substrate for this enzyme. This enables LS to synthesize lactose, the major carbohydrate component of milk. In other tissues, galactosyltransferase transfers galactose onto the N-acetylglucosamine of the oligosaccharide chains in glycoproteins.
Synonyms: LYZL7; LYZG; HAMLET
Tractability: Antibody: UniProt places it where antibodies can reach, with medium confidence; UniProt predicts a signal peptide or a membrane-spanning region; its Gene Ontology location is reachable by antibodies, with medium confidence.
Gene: Protein-coding gene on chromosome 12 (48,567,684 to 48,570,066, reverse strand). Ensembl gene ENSG00000167531.
Subcellular location: Secreted
Pathways (Reactome):
Developmental Biology: Developmental Lineage of Mammary Gland Alveolar Cells
Metabolism: Lactose synthesis
Gene Ontology:
Molecular function: enzyme-substrate adaptor activity; lysozyme activity; calcium ion binding; lactose synthase activity
Biological process: apoptotic process; cell-cell signaling; defense response to bacterium; defense response to Gram-negative bacterium; defense response to Gram-positive bacterium; lactose biosynthetic process; signal transduction
Cellular component: extracellular region; Golgi lumen; Golgi membrane; protein-containing complex
Genetic constraint (gnomAD): Loss-of-function variants: 12 observed, 12.4 expected, observed/expected ratio (o/e) 0.97, 90% interval 0.62 to 1.56. The upper end of that interval is the gene's LOEUF score, 1.56, which puts it in group 6 of 6, group 1 being the genes least tolerant of losing a copy. Missense variants: 122 observed, 138.9 expected, observed/expected ratio (o/e) 0.88, 90% interval 0.76 to 1.02. Synonymous variants: 54 observed, 52.04 expected, observed/expected ratio (o/e) 1.04, 90% interval 0.83 to 1.3.
Homologues: Orthologues: chimpanzee LALBA (99% identical), macaque LALBA (96% identical), dog LALBA (80% identical), pig LALBA (77% identical), guinea pig LALBA (70% identical), rat Lalba (68% identical), mouse Lalba (68% identical), rabbit LALBA (63% identical), Drosophila melanogaster CG8492 (35% identical), Drosophila melanogaster CG11159 (30% identical), Drosophila melanogaster LysS (30% identical), Drosophila melanogaster CG16756 (29% identical), and 8 more. Paralogues in human: LYZ (37% identical), LYZL2 (35% identical), LYZL1 (34% identical), SPACA3 (34% identical), SPACA5 (31% identical), SPACA5B (31% identical), LYZL4 (30% identical), LYZL6 (28% identical).
Diseases named in the same sentence as LALBA in open-access papers:
LALBA is named in the same sentence as 10 diseases in open-access papers, as found by Europe PMC text mining. Sharing a sentence is not in itself a finding about the gene and the disease. The quoted sentences say what the papers report.
breast carcinoma (5 papers, 2020 to 2026). "In particular, lactalbumin alpha (LALBA) and progastricsin (PGC) were replicated with strong evidence of association with breast cancer risk." (PMID 32856720, 2021). "The elevated expression of LALBA may suggest that breast cancer patients are actively undergoing treatment, thereby improving their clinical condition." (PMID 40608007, 2025). "Chromosome 13 open reading frame 42 (C13orf42), lactalbumin alpha (LALBA), G protein-coupled receptor class C group 5 member A (GPRC5A), and GC vitamin D binding protein (GC) have been identified as the most highly expressed genes in breast cancer." (PMID 40608007, 2025). "Furthermore, we tested the expression of FZD2, SFRP2, STK31, and LALBA proteins in canine mammary (CF41 and P114) and human breast cancer cells lines (HCC1500, T47D, DCIS.com, MDA231, and MCF7)." (PMID 32053966, 2020).
colon adenocarcinoma (1 paper, 2008). "LALBA has also recently been implicated in the induction of apoptosis of a human colon adenocarcinoma cell line and RAW264.7 cells." (PMID 18986549, 2008).
mastitis (1 paper, 2025). Inflammation of breast tissue during lactation or postpartum due to an obstructed duct or infection. "High levels of SCC are not only directly related to an increased risk of subclinical mastitis but may also suppress the expression of lactation-related genes and proteins, such as STAT5 and LALBA, through inflammatory factors like IL-6 and TNF-α, leading to decreased milk yield." (PMID 40941289, 2025).
tumor (23 papers, 2009 to 2026). "LALBA, a major milk protein normally expressed only during late pregnancy and lactation, was detected in nearly all tumor samples and showed higher levels in aggressive subtypes, with overexpression displaying a slight trend toward poorer overall survival." (PMID 41683981, 2026).
infection (1 paper, 2020). The state of being infected such as from the introduction of a foreign agent such as serum, vaccine, antigenic substance or organism. "With respect to Jersey breed, peptides resulting from partial digestion of high abundant proteins such as LALBA, CSN2 and CSN3 in the small intestine may influence gut functions including immune stimulation, mineral and trace element absorption and host defence against infection." (PMID 32059637, 2020).
LALBA also shares sentences with these, for which no sentence is quoted: cancer (11 papers); bacterial infection (1); bladder cancer (1); hyperprolactinemia (1); lung carcinoma (1).